KL (klotho)
Diseases named in the same sentence as KL in open-access papers (continued):
Sharing a sentence is not in itself a finding about the gene and the disease.
secondary hyperparathyroidism (15 papers, 2013 to 2026). Overproduction of parathyroid hormone in response to influence external to the parathyroid glands. "Klotho deficiency will impair phosphorus reabsorption in the kidney, leading to secondary hyperparathyroidism and ultimately bone formation disorders." (PMID 37452417, 2023). "Disruption of the fibroblast growth factor 23 (FGF23)–Klotho axis and secondary hyperparathyroidism further exacerbate vascular pathology." (PMID 41470171, 2025). "We believe that elucidation of FGF23-Klotho will provide a different approach in the treatment of refractory secondary hyperparathyroidism." (PMID 25295189, 2014). "Our data challenges the concepts of Klotho as a mandatory factor for the acute hypocalcemic PTH response and decreased Klotho abundance as a pathogenic factor in secondary hyperparathyroidism." (PMID 24348262, 2013). "Effective control of serum phosphorus levels alleviates persistent stimulation of the FGF-23–klotho axis, which may subsequently delay the progression of secondary hyperparathyroidism." (PMID 41601863, 2026). "Additionally, increased Klotho protein expression is beneficial for regenerative tissue response, besides attenuation of proteinuria, secondary hyperparathyroidism, vascular calcification, and ROS damage, improving health span in the kidney disease context." (PMID 34621463, 2021). "Development of secondary hyperparathyroidism could be due to early disturbances on the local calcium sensing receptor, early decline in parathyroid klotho and possibly lower expression of the vitamin D receptor." (PMID 26566277, 2015). "Today, explanation of the FGF23-Klotho axis is becoming increasingly important in order to reveal unknown aspect of the treatment of refractory secondary hyperparathyroidism." (PMID 25295189, 2014). "With a better understanding of the FGF23-Klotho axis, we believe that new approaches might be developed in the treatment of refractory secondary hyperparathyroidism." (PMID 25295189, 2014). "Recent studies have shown that coreceptors Klotho and FGFR1c, which activate FGF-23, decreased in uremic parathyroid hyperplasia, and high serum FGF-23 levels could be explained by Klotho-FGFR1c complexes of secondary hyperparathyroidism." (PMID 25295189, 2014).
hyperlipidemia (14 papers, 2013 to 2025). "Firstly, as this was a cross-sectional survey, it was challenging to establish a precise cause-and-effect relationship between hyperlipidemia and Klotho." (PMID 38027194, 2023). "The study showed a significant association between serum Klotho levels and hyperlipidemia among American adults." (PMID 38027194, 2023). "Studies concerning the association of Klotho with hyperlipidemia prevalence and lipid concentrations are scarce and inconsistent." (PMID 37641103, 2023). "Weighted regression models were fitted to explore the association of Klotho concentrations with hyperlipidemia risk and plasma lipid levels while restricted cubic spline models were applied to explore the dose–response relationship." (PMID 37641103, 2023). "Doubling of serum Klotho concentrations was linked to a 0.81-fold (95%CI: 0.68, 0.95) decreased adjusted risk of hyperlipidemia." (PMID 37641103, 2023). "Serum Klotho concentration was measured by an enzyme-linked immunosorbent assay kit, and the association between Klotho and hyperlipidemia was assessed by a multivariable logistic regression model." (PMID 38027194, 2023). "Higher Klotho concentrations were associated with reduced hyperlipidemia risk and triglyceride levels." (PMID 37641103, 2023). "Subgroup and interaction analyses were performed to explore the influence of age, sex, race/ethnicity, and other relevant factors on the relationship between serum Klotho concentrations and the risk of hyperlipidemia." (PMID 37641103, 2023). "The significant associations between serum Klotho concentrations and hyperlipidemia prevalence as well as plasma lipid levels remained robust in most sensitivity analyses." (PMID 37641103, 2023). "In a nationally representative sample of the U.S. adults, serum Klotho concentrations were negatively associated with hyperlipidemia risk and plasma TG levels, with monotonic dose–response relationships." (PMID 37641103, 2023). "Doubling of serum Klotho concentrations was associated with decreased hyperlipidemia risk (OR = 0.81; 95%CI: 0.68, 0.95) and triglyceride levels (13.25 mg/dL; 95%CI: 4.02, 22.47), with a monotonic dose–response relationship." (PMID 37641103, 2023). "Further investigation is warranted to explore the underlying mechanism between serum Klotho and hyperlipidemia." (PMID 38027194, 2023). "In model 2, the relationship between Klotho and hyperlipidemia remained robust (per SD increment OR: 0.91; 95% CI: 0.86–0.97), indicating that each SD increment in Klotho was associated with a 9% decreased risk of hyperlipidemia." (PMID 38027194, 2023). "Klotho concentrations exhibited an inverse association with the risk of hyperlipidemia and plasma TG levels among nationally representative U.S. adults." (PMID 37641103, 2023). "In our multiple logistic regression models, serum Klotho concentration was significantly associated with hyperlipidemia after adjusting for comprehensive confounders (per SD increment odds ratio (OR): 0.91; 95% confidence interval (CI): 0.86–0.97)." (PMID 38027194, 2023). "Our results suggest that hyperlipidemia-associated kidney injury decreases renal expression of Klotho." (PMID 24386260, 2013). "Similarly, a high Klotho concentration has been confirmed to be associated with a reduced risk of hyperlipidemia, but its mechanism remains to be further explored." (PMID 38713671, 2024). "Association between Klotho and hyperlipidemia among US adults in NHANES 2007–2016." (PMID 38027194, 2023). "Klotho supplementation maybe a promising method to intervene and prevent hyperlipidemia, but the underlying mechanism should be further explored." (PMID 37641103, 2023). "Besides, a significant monotonic dose–response curve between serum Klotho and hyperlipidemia risk was established in the RCS model (Poverall < 0.001, Pnon-linear = 0.074)." (PMID 37641103, 2023). "Sex difference existed in the association between Klotho concentration and hyperlipidemia risk." (PMID 37641103, 2023).
hyperlipidemia (continued). "The aim was to assess the association between serum Klotho levels and hyperlipidemia among adults." (PMID 38027194, 2023). "However, little is known about whether high Klotho concentrations were associated with reduced hyperlipidemia risk and improved plasma lipid levels." (PMID 37641103, 2023). "However, limited evidence exists concerning Klotho levels and the risk of hyperlipidemia." (PMID 38027194, 2023). "In an analysis of a large-scale database, it was also discovered that the reduction of klotho levels has a certain correlation with the high prevalence of hyperlipidemia." (PMID 40452763, 2025). "When serum Klotho was assessed in quartiles, individuals in the highest Klotho quartile had a substantially lower prevalence of hyperlipidemia than those in quartile 1 (OR: 0.72; 95% CI: 0.58–0.90)." (PMID 38027194, 2023). "The median serum Klotho value in the hyperlipidemia group (789.6 pg/mL) was significantly lower compared to the non-hyperlipidemia group (835.4 pg/mL) (P < 0.001)." (PMID 37641103, 2023). "Compared to individuals in the lowest Klotho quartile, those in the highest quartile exhibited a substantially decreased prevalence of hyperlipidemia (OR: 0.72; 95% CI: 0.58–0.90)." (PMID 38027194, 2023). "Our study identified a U-shape relationship between serum Klotho and hyperlipidemia, with an inflection point of 1,365.5 pg/mL." (PMID 38027194, 2023). "Individuals in the fourth and fifth quintile of serum Klotho respectively had adjusted odds ratios (OR) of 0.77 (95%CI: 0.65, 0.93) and 0.67 (95%CI: 0.65, 0.93) for hyperlipidemia, with a significant linear trend (Ptrend < 0.001)." (PMID 37641103, 2023). "On the left side of this inflection point, the OR (95% CI) between Klotho concentration and hyperlipidemia prevalence was 0.9996 (0.9994, 0.9998)." (PMID 38027194, 2023). "This research investigated the potential relationship between Klotho levels and hyperlipidemia in the American population, using data from the National Health and Nutrition Examination Survey (NHANES)." (PMID 38027194, 2023). "Our results indicated an inverse relationship between Klotho levels and hyperlipidemia, even after adjusting for covariates and performing subgroup analyses." (PMID 38027194, 2023). "The study aimed to investigate the potential relationship between serum Klotho concentration and the prevalence of hyperlipidemia." (PMID 38027194, 2023). "Using a two-segment logistic regression model, we identified a U-shaped relationship between serum Klotho concentration and hyperlipidemia, with an inflection point at 1,365.5 pg/mL." (PMID 38027194, 2023). "Using a two-segment logistic regression model, we identified a U-shaped relationship between serum Klotho and hyperlipidemia, with a distinct inflection point at 1,365.5 pg/mL." (PMID 38027194, 2023). "Herein, we conducted a cross-sectional study to examine serum Klotho levels in relation to the prevalence of hyperlipidemia, as well as lipid concentrations, in U.S. adults." (PMID 37641103, 2023). "Individuals in the fourth and fifth quintile of serum Klotho had an adjusted odds ratio (OR) of 0.77 (95%CI: 0.65, 0.93) and 0.67 (95%CI: 0.65, 0.93) for hyperlipidemia." (PMID 37641103, 2023). "We specifically explored the relationship between Klotho concentrations and the prevalence of hyperlipidemia, as well as plasma lipid levels." (PMID 37641103, 2023). "In our study, we observed that renal Klotho mRNA and protein expression decreased as hyperlipidemia increased." (PMID 24386260, 2013). "In conclusion, the present study reveals that hyperlipidemia induces inflammation, oxidative stress and accelerates renal damage in ApoE KO mice; and this is accompanied by down-regulation of Klotho expression." (PMID 24386260, 2013). "In this article we provide evidence for a role of hyperlipidemia in attenuation of Klotho expression." (PMID 24386260, 2013).
hyperlipidemia (continued). "Serum Klotho concentrations were linked to decreased hyperlipidemia risk in elder, female, Non-Hispanic black, and participants with high BMI and educational level." (PMID 37641103, 2023). "However, we observed no significant mediation effects of CRP on the relationships between serum Klotho concentrations and the prevalence of hyperlipidemia, as well as plasma lipid levels." (PMID 37641103, 2023). "Serum Klotho concentrations displayed a negative association with hyperlipidemia risk, even after accounting for various confounding factors." (PMID 37641103, 2023). "This study revealed an inverse relationship between Klotho levels and hyperlipidemia." (PMID 38027194, 2023). "However, no previous assessments have been made regarding the impact of plasma Klotho on lipid metabolism or the potential correlation between hyperlipidemia and Klotho levels." (PMID 38027194, 2023). "Besides, higher serum Klotho concentrations were associated with lower CRP levels, yet no substantial mediation effect of CRP on the relationships of serum Klotho concentrations with the prevalence of hyperlipidemia and plasma lipid levels were observed." (PMID 37641103, 2023). "Therefore, our study offers credible data for future research to uncover the underlying mechanisms of the relationship between the anti-aging protein Klotho and hyperlipidemia." (PMID 38027194, 2023). "Threshold analyses of serum Klotho on hyperlipidemia using two-segment regression models." (PMID 38027194, 2023). "Building upon these benchmark data, we sought to explore the impact of prolonged hyperlipidemia as well as the effect colchicine-based therapy on a variety of atheroprotective (Klotho, HOXA5, NOTCH1, and OCT4) and proatherogenic (HIF1a, SOX2, BMP4, and NANOG) genes." (PMID 36362692, 2022). "Therefore, to analyze the mechanisms involved in the modulation of Klotho by hyperlipidemia in vivo, we incubated cultured renal cells in presence of ox-LDL." (PMID 24386260, 2013). "The same results were obtained when we determined Klotho mRNA expression by quantitative RT-PCR, suggesting that hyperlipidemia could downregulate renal Klotho expression." (PMID 24386260, 2013). "However, we observed negative associations of Klotho concentrations with hyperlipidemia risk among the elderly and individuals with high BMI levels." (PMID 37641103, 2023). "However, there is limited understanding of the connection between Klotho and hyperlipidemia." (PMID 38027194, 2023). "Therefore, Klotho could be a key element explaining the relationship between hyperlipidemia and aging with renal disease." (PMID 24386260, 2013). "We evaluated whether hyperlipidemia modulates Klotho expression in kidneys from C57BL/6 and hyperlipidemic apolipoprotein E knockout (ApoE KO) mice fed with a normal chow diet (ND) or a Western-type high cholesterol-fat diet (HC) for 5 to 10 weeks, respectively." (PMID 24386260, 2013). "In our study, we found that there was a slight negative correlation between the SII and serum Klotho levels in different BMI groups and hyperlipidemia in OA patients, but more studies are needed in the future to provide stronger epidemiological evidence." (PMID 38713671, 2024). "The beneficial effect of Klotho on hyperlipidemia control was more prominent in elder, female, Non-Hispanic black, and adults with high educational levels." (PMID 37641103, 2023). "We employed a smoothed curve fitting to illustrate the nonlinear relationship between Klotho levels and hyperlipidemia." (PMID 38027194, 2023). "Hyperlipidemia is accompanied by formation of ox-LDL, leading to increased oxidative stress and inflammatory cytokine production, changes that could modulate Klotho expression." (PMID 24386260, 2013). "Furthermore, we identified a nonlinear relationship between Klotho and hyperlipidemia." (PMID 38027194, 2023).
premature aging syndrome (14 papers, 2013 to 2025). Changes in the organism associated with senescence, occurring at an accelerated rate. "KL refers to α-Klotho, which was first identified in a study of KL-deficient mice that developed multiple premature aging syndromes, contrasted with KL-overexpression associated with the extended lifespan of the mice." (PMID 38267588, 2024). "Klotho gene deficiency mice exhibit premature aging syndrome, accompanied with significant VC, and genetic overexpression of Klotho or administration of soluble Klotho rescues the Klotho-deficient phenotype and VC." (PMID 36742073, 2023). "Klotho’s absence led to premature aging syndrome, the “Klotho-deficient mice aging model”, while in an animal model with Klotho overexpression, life expectancy increased." (PMID 35055149, 2022). "The klotho deficient mice due to a defect in klotho gene expression display multiple aging-like phenotypes similar to human premature-aging syndromes." (PMID 33413301, 2021). "The klotho (KL) gene, named after the Greek goddess said to spin the thread of life, was identified in 1997 as a gene mutated in the klotho mouse, which has an extremely short life span and suffers from multiple disorders resembling human premature-aging syndromes." (PMID 24714085, 2014). "Klotho (KL) is a membrane‐bound protein that plays an anti‐ageing role because Kl‐null mice exhibit phenotypes similar to human premature ageing syndromes." (PMID 33438362, 2021). "The klotho gene has been suggested in 1997 using klotho mutant mice (kl/kl mice) with multiple disorders similar to human premature-aging syndrome." (PMID 24683546, 2014). "Klotho was first found in 1997 as a putative aging-suppressor gene in mice that extended life span when overexpressed and induced a premature aging syndrome when disrupted." (PMID 23437382, 2013).
vitamin D deficiency (14 papers, 2016 to 2025). A nutritional condition produced by a deficiency of VITAMIN D in the diet, insufficient production of vitamin D in the skin, inadequate absorption of vitamin D from the diet, or abnormal conversion of vitamin D to its bioactive metabolites. "Collectively, these findings highlight PLA2hyperactivity, vitamin D deficiency, Klotho loss, and ATGL dysfunction as pivotal determinants of AIP elevation in CKD." (PMID 40520802, 2025). "In the end stage, phosphate overload and vitamin D deficiency down-regulate klotho expression in the kidney, which in turn decreases FGF23 affinity to FGF receptors and results in FGF23 resistance." (PMID 37422767, 2024). "In a previous study of CKD progression, we showed that vitamin D deficiency caused a reduction in Klotho expression in rats euthanized 60 days after I/R injury." (PMID 30370270, 2018). "We observed that vitamin D deficiency decreased Klotho protein expression in VDD+Nx rats in comparison to Nx rats." (PMID 30370270, 2018). "The mineralization defects in Klotho−/− mice were possibly resulted from enhanced vitamin D signaling since Klotho could restrain trabecular bone defects due to vitamin D deficiency." (PMID 39465174, 2024). "Some earlier studies showed that high levels of the biomarkers sclerostin, osteoprotegerin, FGF or FGF-KLOTHO axis, and/or vitamin D deficiency correlated positively with AS, while others did not confirm the association of these biomarkers with AS in prevalent hemodialysis patients." (PMID 32872092, 2020). "In addition, vitamin D deficiency reduced Klotho gene expression in VDD+Nx rats compared to Nx rats." (PMID 30370270, 2018). "Several factors contribute to downregulate Klotho expression in CKD, including uremic toxins, vitamin D deficiency, phosphate overload, activation of RAAS, oxidative stress, and inflammation." (PMID 30208590, 2018). "In the presence of klotho and FGF23, the diet becomes critically important only during vitamin D deficiency." (PMID 27109615, 2016). "However, in the context of CKD-MBD, factors such as hypocalcemia, vitamin D deficiency, dysregulation of the FGF23-Klotho axis, as well as other internal environmental disturbances, can lead to dysfunction of these channels." (PMID 40417213, 2025).